TNFRSF14 (TNF receptor superfamily member 14)
Diseases named in the same sentence as TNFRSF14 in open-access papers (continued):
Sharing a sentence is not in itself a finding about the gene and the disease.
thyroid MALT lymphoma (2 papers, 2021 to 2025). "Similarly, most TNFRSF14 mutations in thyroid MALT lymphoma were also likely deleterious." (PMID 34021249, 2021). "We correlated TET2, TNFRSF14, CD274 and TNFAIP3 mutation AAF in thyroid MALT lymphoma in order to understand the sequence of their occurrence." (PMID 34021249, 2021). "We found frequent deleterious mutations of TET2 (86%), CD274 (53%), TNFRSF14 (53%), and TNFAIP3 (30%) in thyroid MALT lymphoma." (PMID 34021249, 2021). "Taken together, inactivation of both CD274 (PD-L1) and TNFRSF14 in thyroid MALT lymphoma most likely abolishes their negative regulation to T-helper cells, hence enhances their function, leading to exaggerated T-cell help to support malignant B-cells." (PMID 34021249, 2021). "Recent molecular studies have started to identify genetic changes, like those in TET2 and TNFRSF14, that may explain the biology of thyroid MALT lymphoma." (PMID 41583202, 2025).
aortic aneurysm (1 paper, 2022). A ruptured aneurysm located in the wall of the proximal portion of the descending aorta proceeding from the arch of the aorta. "FOXP3+ Treg cells were abundant in aortic aneurysms, especially in AAA groups and displayed high expression of exhausted genes CTLA4, TIGIT, TNFRSF14, ICOS, and CD28." (PMID 36703732, 2022).
celiac disease (1 paper, 2015). An autoimmune genetic disorder with an unknown pattern of inheritance that primarily affects the digestive tract. "TNFRSF14 (rs2234167), a strong candidate for celiac diseases, which is less than 60 kb downstream is in strong linkage (r2 = 0.89) with rs3890745 of MMEL1 further raising the possibility of its indirect involvement in celiac disease." (PMID 26843707, 2015).
gastric MALT lymphoma (1 paper, 2021). "The frequency of TNFAIP3, TET2, and NOTCH1 mutations in H. pylori negative gastric MALT lymphoma is similar to those seen in unselected gastric MALT lymphomas, whereas the previously reported TNFRSF14 alterations affecting gastric MALT lymphomas were absent in the current series." (PMID 34203889, 2021).
Li (1 paper, 2022). "The upregulation of TNFRSF14/TNFRSF14-AS1 pair occurred upon Lb and Li infection." (PMID 36685903, 2022).
lymph node metastasis (1 paper, 2021). "The high expression of TNFRSF14 was associated with tumor size, TNM stage and lymph node metastasis." (PMID 34380460, 2021).
malignant glioma (1 paper, 2024). A grade III or grade IV glioma arising from the central nervous system. "TNFRSF14 is a potential suitable target for developing new ICB strategies in malignant glioma, and the combination of TNFRSF14 blockade with anti-PD-L1 provides synergic benefit for GBM." (PMID 39085878, 2024).
multiple sclerosis (1 paper, 2021). A progressive autoimmune disorder affecting the central nervous system resulting in demyelination. "HVEM (TNFRSF14) rs6684865 was related to primary sclerosing cholangitis (PSC), RA, and multiple sclerosis (MS)." (PMID 34238277, 2021).
pancreatic ductal adenocarcinoma (1 paper, 2020). An infiltrating adenocarcinoma that arises from the epithelial cells of the pancreas. "But many key feature genes, such as TNFRSF14, XPO1, and ATF3, showed great promise on explaining perineural invasion in pancreatic ductal adenocarcinoma." (PMID 33193628, 2020). "The in-depth biological analysis of key feature genes, such as TNFRSF14, XPO1, and ATF3, shed light on the understanding of perineural invasion in pancreatic ductal adenocarcinoma." (PMID 33193628, 2020).
spontaneous abortion (1 paper, 2024). Expulsion of the product of FERTILIZATION before completing the term of GESTATION and without deliberate interference. "Further, we found excessive uterine senescence, SLC3A2-mediated BCAA intake, and insufficient TNFRSF14 expression in the decidua of patients with recurrent spontaneous abortion." (PMID 39261664, 2024). "In summary, this study suggests that dNK cells maintain senescence homeostasis of DSCs via TNFSF14/TNFRSF14, providing a potential therapeutic strategy to prevent DSC senescence-associated spontaneous abortion." (PMID 39261664, 2024).
uveal melanoma (1 paper, 2021). A melanoma derived from melanocytes of the uveal tract. "In GSE155452 uveal melanoma cell line (mel202), after romidepsin intervention, the expression of CD274 was significantly increased, and the expression of TNFRSF9 and TNFRSF14 was significantly different." (PMID 34635662, 2021).
tumor (174 papers, 2012 to 2026). "Conversely, genes such as TNFSF14 (LIGHT) and TNFRSF14 (HVEM), which promote anti-tumor immunity, showed higher expression in the low-risk group." (PMID 41153362, 2025). "TNFRSF14 activation can serve as a biomarker in evaluating various cancers’ prognosis, as it is closely associated with tumor growth and metastasis." (PMID 36253800, 2022). "TNFRSF14 is located on the short arm of chromosome 1q36 and can regulate a series of immune responses, including anti-tumor immunity, by encoding a type I transmembrane molecule." (PMID 36253800, 2022). "Additional mutations, such as loss-of-function mutations of HVEM/TNFRSF14 or the introduction of N-glycosylation sites within Ig variable regions, have been shown to affect the crosstalk between tumor B cells and their surrounding microenvironment." (PMID 36358756, 2022). "We found that CD8+ T cells and M2 macrophages were closely related to TNFRSF14 and APOL2, and the expression of TNFRSF14 and risk score were strongly associated with tumor purity, immune score, various inflammatory factors, and others." (PMID 34708131, 2021). "Further analysis showed that TNFRSF14 expression was significantly associated with tumor stage, mutant types, and histological types of EC." (PMID 34158412, 2021). "All of them were found to be highly expressed in the high-risk scoring group, except for TNFRSF14, suggesting that the high-risk group may further inhibit effective anti-tumor immune responses." (PMID 38714855, 2024). "Among them, the frequent mutations of TNFRSF14/HVEM could play a role in the maintenance of the functional tumor cell niche." (PMID 22973275, 2012). "Mutations in TNFRSF14 may lead to a tumor-supportive microenvironment through an increase in the production of cytokines recruiting T follicular helper cells, and mutations in B2M may lead to loss of expression of human leukocyte antigen class 1, which impairs CD8+ cytotoxic T-cell binding." (PMID 39392347, 2024). "ETV4 and ETV5 of the ETS family are involved in cancer stemness and metabolic reprogramming, whereas TNFRSF14 inhibits tumor growth through apoptotic signaling." (PMID 41304759, 2025). "In ascitic CD4+ T cells of tumor‐bearing mice, Tnfrsf14 knockdown resulted in a reciprocal increase in IFNγ‐producing Th1 cells and a decrease in IL4‐producing Th2 cells, whereas the levels of IL17‐producing Th17 cells remained similar." (PMID 40105652, 2025). "In this study, we revealed the differential expression of TNFRSF14/HVEM as a tumor promoter and identified its dominant expression in CD45−EpCAM+ subsets in OvCa." (PMID 40105652, 2025). "Several elevated ligand-receptor pairs in CML were related to cancer development, such as ADRB2_VEGFB, which was involved in tumor angiogenesis, and BTLA_TNFRSF14, which was reported in immune regulation." (PMID 40612663, 2025). "Although the role of the herpesvirus entry mediator (HVEM), encoded by the TNFRSF14 gene, is currently considered pivotal in various types of cancer, the regulation of tumor cell‐expressed HVEM in OvCa remains inadequately understood." (PMID 40105652, 2025). "Targeting TNFRSF14 alongside immune checkpoint inhibition was observed to inhibit tumor proliferation and induce disulfidptosis in tumor cells." (PMID 38292868, 2024). "The upregulation of TNFRSF14 in tumor cells contributes to the inhibition of antitumor resistance by BTLA, leading to disease development and worse diagnostic outcomes 50,51." (PMID 39440068, 2024). "We observed not only an extended survival in TNFRSF14 knock-down group mice, but also remarkably reduced tumor volume and decreased Ki-67 staining intensity in tumor samples from these mice." (PMID 39085878, 2024).
tumor (continued). "Through screening, TNFRSF14 was identified as the candidate for further investigation, which have both of cancer intrinsic and non-tumor cell expression in GBM." (PMID 39085878, 2024). "Correlation analysis indicated positive associations of CD160 ligands such as TNFRSF14 and HLA-C, and NKG2D (KLRK1) ligands MICA and MICB with the tumour-infiltrating CD56bright NK and CD8+ TEM cells." (PMID 39877370, 2024). "The results showed that CD200, CD80 and TNFRSF14 were the highest in tumor tissues, CD274 (PDL1), CD86, LGALS9, NECTIN2, PDL2, PVR were lower than those in adjacent tissues but higher than those in normal tissues, and FGL1 was the lowest in tumor tissues." (PMID 39120585, 2024). "Neutralizing upregulated IFN-γ induced by PD-L1 treatment significantly attenuated TNFRSF14 expression in tumor derived from mGSCs in immune competent mice model." (PMID 39085878, 2024). "We further employed human THP-1 cells and mouse BMDMs to perform in vitro functional assays to examine the potential influence of tumor-intrinsic TNFRSF14 on macrophages." (PMID 39085878, 2024). "This implicates the potential survival benefit brought by TNFRSF14 blockade through restraining pro-tumorigenic effect of non-tumor cell components in TME." (PMID 39085878, 2024). "In comparison to anti-TNFRSF14 mono-treatment, the combination of TNFRSF14 and PD-L1 blockade remarkably extend the survival of tumor-bearing mice." (PMID 39085878, 2024). "Tnfrsf14 knockdown in mGSCs significantly restrained their tumorigenicity and extended the survival of tumor-bearing mice, with reduced tumor volume and lower Ki-67 expression." (PMID 39085878, 2024). "While IFN-γ sensing program induces TNFRSF14 upregulation in tumor cells, this cancer intrinsic TNFRSF14 elevation augments the recruitment of anti-inflammatory TAMs in preclinical mouse GBM model." (PMID 39085878, 2024). "According to FACS analysis, TNFRSF14 ablation in mouse GBM cells efficiently decreased the ratio of CD206+/MHC II+ TAMs in mouse GBM tumor tissues." (PMID 39085878, 2024). "Recurrent TNFRSF14 mutations in DHLs lead to reduced expression of HVEM, a TNFR family protein and tumor suppressor which inhibits BCR signaling, abnormal stroma activation, and CD40 signaling through BTLA stimulation." (PMID 35303910, 2022). "Results revealed that high FAS, TNFRSF14, TNFRSF17, TNFRSF1B, and TNFSF13B expressions are associated with a high probability of “hot” tumor." (PMID 36588791, 2022). "The immune checkpoint TNFSF14 in Neutrophils, NK Cells, and Monocytes and BTLA in Treg Cells, Granulosa Cells, and B Cells interact with LTBR and TNFRSF14 in Cancer Cells to mediate cytotoxicity and promote tumor killing." (PMID 36401283, 2022). "In the correlation analysis of MB purity and the immune microenvironment, three genes related to immunity, namely, CD8A, CXCR2, and TNFRSF14, were negatively related to tumor purity." (PMID 34925437, 2021). "Recently, a new co-inhibitory pair was identified as a checkpoint of the anti-tumor immune response: HVEM (herpes virus entry mediator, TNFRSF14) and BTLA (B and T lymphocyte attenuator)." (PMID 34208480, 2021). "We noted that high BLCA tumor expression of TNFRSF14 or CD160 trended toward improved prognosis compared with either TNFSF14, LTA, or BTLA." (PMID 34858395, 2021). "The mRNA expression of TNFRSF14 was detected by RT-qPCR, and we observed that its expression was significantly elevated in tumor tissues." (PMID 34380460, 2021). "The expression of TNFRSF14 in tumor tissues was significantly and negatively correlated with the expression of MYH11." (PMID 34380460, 2021). "We found that LGALS9_CD44, MIF_TNFRSF14, CD47_SIRPG, MDK_LRP1 and LGALS9_HAVCR2, CD74_COPA, C3_C3AR1, ANXA1_FPR3 interactions were upregulated in both ductal-tumor and malignant cells versus ductal-normal." (PMID 35087839, 2021). "Thus, TNFRSF14/HVEM specifically altered the frequency of lymphoid cells in the tumor microenvironment of OvCa mice." (PMID 40105652, 2025).
tumor (continued). "On the other hand, overexpression of TNFRSF14 inhibits the proliferation of cancer cells, suggesting that this protein may be a tumor suppressor." (PMID 40362653, 2025). "We evaluated the function of T cells within the tumor microenvironment influenced by TNFRSF14/HVEM." (PMID 40105652, 2025). "Notably, in addition to promoting cancer cell proliferation, we demonstrated the immunosuppressive role of tumor cell‐expressed TNFRSF14/HVEM in accelerating OvCa progression." (PMID 40105652, 2025). "For stimulating effects, ICIs can induce an enhanced expression of tumor cell ISGs transcribing additional T-cell co-inhibitory ligands (e.g., TNFRSF14, LGALS9) where blockade of type I and II IFN signaling could reverse this effect and improve ICI responses." (PMID 39663510, 2025). "In summary, TNFRSF14/HVEM expression in tumor cells promotes Stat5 and Stat6 activation." (PMID 40105652, 2025). "TNFRSF14 may therefore be overexpressed as an anti-tumour response to the presence of disease, which could explain our findings." (PMID 38750076, 2024). "Overexpressed TNFRSF14 promoted the proliferation capabilities of tumor cells." (PMID 39085878, 2024). "Moreover, IHC staining analysis demonstrated that more CD86+ TAMs, CD8+ T cells and perforin were observed in tumor samples derived from Tnfrsf14-knockdown GL261 and mGSC cells." (PMID 39085878, 2024). "Notably, we observed that PD-L1 blockade led to IFN–γ elevation in mouse immune competent GBM tumor, while inducing TNFRSF14 upregulation in these samples." (PMID 39085878, 2024). "B and T lymphocyte attenuator (BTLA) in tumor cells could inhibit the activation of B cells, T cells, and macrophages by binding to TNFRSF14." (PMID 37173968, 2023). "In the tumor microenvironment, TNFRSF14 is crucial for immune system activation and recruitment." (PMID 36911389, 2023). "Besides, our results also found that some inhibitory interactions, such as SIRPG-CD47 and TNFRSF14-TNFSF14 interactions were detected between MRS1-tumor cells and MRS1-T cells." (PMID 37543645, 2023). "TNFSF14 binds with TNFRSF14 to deliver costimulatory signals to T cells that are capable of causing significant changes in the TME and induce an anti-tumor immune response, indicating that they might be useful in enhancing cancer immunotherapy." (PMID 36002754, 2023). "The expression of TNFRSF14 was enhanced in tumor tissues relative to adjacent tissues." (PMID 34380460, 2021). "All samples share identical TNFRSF14 missense mutation irrespective of lesion type (plaque/tumor) being conserved over a time course of 12 months." (PMID 34771672, 2021). "We first detected the expression of TNFRSF14 in GC tumor tissues and their adjacent tissues by IHC." (PMID 34380460, 2021). "Interestingly, TNFRSF14 is also expressed by many tumor cells including BLCA, and TNFRSF14 ligation can induce BLCA cell apoptosis." (PMID 34858395, 2021). "TNFRSF14 mediates apoptosis and inhibits tumor cells from undergoing immune escape." (PMID 34708131, 2021). "TNFRSF14 mediates apoptosis and prevents tumor cells from immune escape." (PMID 35237614, 2021). "Noteworthily, the high-risk group indicated lower expression levels of CD200, NRP1, and TNFRSF14, suggesting that tumor cells might evade immune surveillance through inhibiting the function of these immune checkpoint genes, which could subsequently affect patient prognosis." (PMID 40365116, 2025). "Mice with TNFRSF14 antibody treatment, especially the combination treatment group, exhibited significantly decreased tumor growth and lower ratio of Ki67 staining positive cells in tumor tissues compared to control group and anti-PD-L1 mono-treatment group, respectively." (PMID 39085878, 2024).